BRCA2 (BRCA2 DNA repair associated)
Diseases named in the same sentence as BRCA2 in open-access papers (continued):
Sharing a sentence is not in itself a finding about the gene and the disease.
breast cancer (continued). "By age 85 years, for BRCA2 carriers, the breast cancer risk varied from 7.7% to 18.4% and prostate cancer risk from 34.1% to 87.6% between the 5th and 95th percentiles of the PRS distributions." (PMID 34320204, 2022). "Loss of heterozygosity (LOH) event was identified in the pathogenic BRCA2 germline mutation in the breast cancer sample alone, indicating the driving role of this mutation in breast cancer." (PMID 35912179, 2022). "BRCA1 mutations in breast cancer epithelial cells lead to the loss of H3K27ac at super enhancers and impair enhancer–promoter lopping, whereas BRCA2 depletion has been linked to chromatin remodelling." (PMID 35326684, 2022). "The risk ratio for bilateral breast cancer is approximately four times when compared BRCA2 (17%) and other counselled patients’ group (4%) (p < 0.05)." (PMID 35469032, 2022). "In all three relatives, BRCA2 mutations have been detected, which increase the lifetime risk of breast cancer to around 60–70% and of ovarian cancer to 20–30%." (PMID 36083315, 2022). "Accordingly, cells with impaired HR, for example those harboring pathogenic mutations in breast cancer genes BRCA1 or BRCA2, are hypersensitive to PARP inhibitors and persistently accumulate DSB due to the error-prone NHEJ." (PMID 35456968, 2022). "Men with BRCA2 PV have approximately a 6% risk of breast cancer, for men with BRCA1 PV the risk is approximately 1%13." (PMID 35469032, 2022). "BRCA2‐associated breast cancers are more likely to be hormone receptor positive (HR+) and have lower tumor grade and mitotic counts compared to BRCA1‐associated breast cancers." (PMID 35128817, 2022). "The research conducted in Poznań shows that the frequency of mutations of the BRCA2 gene is also increased in families with breast cancer in men and it amounts to about 15% in Poland." (PMID 35395863, 2022). "Because loss of BRCA2 is associated with susceptibility to breast cancer, we generated two clonal cell lines with stable BRCA2 knockdown in the breast cancer cell line MDA‐MB231to assess synthetic lethality with SIK2 in a relevant cancer type." (PMID 34058059, 2022). "In carriers of the BRCA1 and BRCA2 pathogenic variants, prophylactic mastectomy reduces the risk of subsequent breast cancer by approximately 90%." (PMID 36580360, 2022). "The combination of radiation therapy with PARP inhibitors for cases of BRCA2-mutated canine mammary tumors is also being studied." (PMID 36548864, 2022). "Further, patients with TN breast cancer aged 35-49 years in stage I with the BRCA2 pathogenic variant in exon 11 had a very modest benefit from RRBM-RRBSO." (PMID 36580360, 2022). "At present, no personalized guidelines are available for the prophylactic management of second primary breast cancer in patients with the BRCA1 and BRCA2 pathogenic variants with unilateral breast cancer who underwent BCT as a primary procedure." (PMID 36580360, 2022). "Risk factors for male breast cancer include a family history of breast and ovarian cancer, BRCA2 mutation, Klinefelter syndrome, old age, obesity, use of estrogen preparations, and exposure to radiation." (PMID 35252796, 2022). "In approximately 63% of patients with breast cancer related to the pathogenic variant BRCA1 or BRCA2, genetic testing was performed after surgery of the primary cancer, with 62% of these patients also undergoing a primary breast-conserving treatment (BCT)." (PMID 36580360, 2022). "Olaparib, a poly(ADP-ribose) polymerase (PARP) inhibitor that has just been approved for use in Japan, was shown to be effective for CRPC with breast cancer 1, breast cancer 2 (BRCA2), or ATM serine/threonine kinase mutations in the PROfound trial." (PMID 35725469, 2022). "More recently, it was shown that phosphorylation of BRCA2, which is often mutated in breast cancer patients, by Plk1 is important for the formation of a complex between BRCA2, BubR1, and the phosphatase PP2A." (PMID 35563837, 2022).
breast cancer (continued). "The prognostic role of BRCA mutations in ovarian and breast cancer is well established; BRCA2 mutated breast cancer displays worse prognosis compared to sporadic cancer, while, in BRCA1, no substantial differences were observed." (PMID 35200549, 2022). "Similar frequencies were also previously reported in unselected Japanese breast cancer patients, with BRCA2 mutations observed in 2.71%, and BRCA1 mutations observed in 1.45% of the patients." (PMID 35494038, 2022). "Different risk assessment models examined performed well in predicting risk of carrying germline loss-of-function variants in BRCA1 and/or BRCA2 in breast cancer cases." (PMID 35353237, 2022). "The study has successfully identified candidate variants on breast cancer including variants in BRCA2 gene." (PMID 36268271, 2022). "Breast cancer patients carrying BRCA1 or BRCA2 germline mutations have a mean onset age of 40 and 43 years, respectively, and patients carrying PALB2 mutations have a mean onset age of 53 years." (PMID 35494038, 2022). "The array comparative genomic hybridisation (aCGH) BRCA1-like and BRCA2-like classifiers are two HRD-tests that have been developed from the characteristic DNA copy number aberrations of BRCA1- and BRCA2-mutated breast cancers, respectively." (PMID 35124703, 2022). "A breast cancer gene 1 (BRCA1) or BRCA2 gene mutation is thought to be responsible for 2% to 3% of all cases of BC." (PMID 35889394, 2022). "The impact of RRBSO in patients with the BRCA1 and BRCA2 pathogenic variants with luminal breast cancer in stage I/II increased with age." (PMID 36580360, 2022). "BRCA2 mutation has been linked to many cancer types, including breast cancer, ovarian cancer, pancreatic cancer and glioblastoma." (PMID 36686473, 2022). "An earlier study by the Breast Cancer Chain Association found a 3.5-fold increased risk of pancreatic cancer in BRCA2 mutations." (PMID 36397405, 2022). "The frequency of germline BRCA1/2 gene mutation carriers and the ratio of germline BRCA1 to BRCA2 mutations in BRCA-related breast cancer patients vary depending on the population." (PMID 36230696, 2022). "Considering the LOH event of BRCA2 in breast cancer and BRCA2 p.S744X somatic mutation in gastric cancer, BRCA2 p.Y1894* mutation is prone to a second-hit event of BRCA2 in them." (PMID 35912179, 2022). "This is partially consistent with similar finding that the inheritance of defective BRCA1 or BRCA2 allele predisposes an individual to develop breast cancer." (PMID 36038839, 2022). "The risk of germline copy number variants (CNVs) in BRCA1 and BRCA2 pathogenic variant carriers in breast cancer is assessed, with CNVs overlapping SULT1A1 decreasing breast cancer risk in BRCA1 carriers." (PMID 36203093, 2022). "Some RAD52 mutations that affect the SSA function or decrease RAD52 association with DNA can suppress certain BRCA2 associated phenotypes in breast cancers." (PMID 36107942, 2022). "Elucidation of specific and recurrent/founder pathogenic variants (PVs) in BRCA (BRCA1 and BRCA2) genes can make the genetic testing, for breast cancer (BC) and/or ovarian cancer (OC), affordable for developing nations." (PMID 35216584, 2022). "We and others have shown that variants affecting the expression levels of BRCA1 and BRCA2 modify the risk of breast cancer in germline mutation carriers." (PMID 35676284, 2022). "In our study, five mutations (in BRCA1 and in BRCA2) were OCCRs, which means they had higher ovarian cancer risk and lower breast cancer risk than mutations in other regions." (PMID 35205313, 2022). "Germline mutations in BRCA1 or BRCA2 exist in ~2–7% of breast cancer patients, which has led to the approval of PARP inhibitors in the advanced setting." (PMID 35538088, 2022). "In population studies unselected for family history, 4–33% of male breast cancer patients harbor BRCA2 mutations and 0–6% harbor BRCA1 mutations." (PMID 35656339, 2022).
breast cancer (continued). "Mutations in the BRCA2 gene are responsible for tumors in breast cancer in 31–56%, ovarian cancer 11–27% and have been found in families with male breast cancers." (PMID 35395863, 2022). "Meta-analysis of these studies of 108,699 unselected breast cancer cases showed that 3.4% of breast cancers occurred in patients with a germline pathogenic variant of BRCA1 or BRCA2 (95% CI 2.5–4.7)." (PMID 35805038, 2022). "Regarding pharmacological prevention, only a small sample of retrospective studies has shown that tamoxifen reduces the risk of breast cancer in healthy carriers of the BRCA2 gene mutation by 62% (288 cases, 11 with BRCA2 mutation)." (PMID 36397405, 2022). "In ultrasound examination, BRCA1 and BRCA2-mutated breast cancer demonstrates an irregular shape and blurred boundary hypoechoic masses." (PMID 35402620, 2022). "In our cohort there was an equal proportion of women who carried a deleterious variant in BRCA1/BRCA2 (1.8%) and women who carried a deleterious variant in other breast cancer susceptibility genes (1.8%)." (PMID 35039564, 2022). "It has been demonstrated that environmental exposure to certain toxins can induce haploinsufficiency, a mechanism proposed to contribute to breast cancer development, especially in BRCA2 cells bearing heterozygous mutations." (PMID 35875117, 2022). "As a disease of the genome, cancer development has a clear Mendelian component, demonstrated by several famous genes such as BRCA1 and BRCA2 in breast cancer risk." (PMID 35459932, 2022). "There was a negligible increase in survival in almost all carriers of the pathogenic variants of BRCA1 and BRCA2 with TN breast cancer in stage II who underwent any secondary risk–reducing strategy compared with surveillance." (PMID 36580360, 2022). "RAD51 mediated HR generally results in error-free repair but requires the breast cancer susceptibility gene BRCA2 which facilitates RAD51 loading onto the resected single stranded DNA." (PMID 36107942, 2022). "For example, the OB-fold domain in the breast cancer susceptibility protein BRCA2 represents an attractive cancer drug target." (PMID 36432892, 2022). "Multiple pathogenic variants of the BRCA1 and BRCA2 genes that confer high relative risks of breast cancer have been identified." (PMID 35395775, 2022). "In the case of the BRCA2 mutation, carriers have more or less the same risk of developing breast cancer." (PMID 36230696, 2022). "Mutations in DNA damage response genes, such as BRCA1 and BRCA2, observed in breast cancer are also associated with production of elevated mutation numbers, particularly of strong binder peptides to MHC molecules." (PMID 35323317, 2022). "RAD51 is a recombinase that directly interacts with the breast cancer-associated tumor suppressor BRCA2 and this interaction is critical for normal recombination proficiency." (PMID 36243983, 2022). "We performed a meataanalysis of BRCA1 or BRCA2 germline pathogenic or likely pathogenic variant (gBRCA) in 108,699 unselected breast cancer patients and in 238,972 unaffected individuals." (PMID 35805038, 2022). "Studies have shown that the major risk factors for the development of male breast cancer include advancing age, hormonal imbalance, radiation exposure, and a family history of breast cancer, but the most relevant risk factor is mutations in the BRCA2 gene." (PMID 35918668, 2022). "In the following years, the BRCA2 variant was also detected in one of his sisters, who developed breast cancer at age 44, and in one of his healthy daughters." (PMID 36292468, 2022). "According to a meta‐analysis of BRCA1 and BRCA2 carrier families, the lifetime risk of breast cancer varies from 65% to 81% for BRCA1 and 45% to 85% for BRCA2." (PMID 35762299, 2022). "BRCA1 and BRCA2 germline pathogenic variants (GPVs) account for most of the 5-10% of breast cancer (BC) that is attributable to inherited genetic variants." (PMID 36119527, 2022).
breast cancer (continued). "In the report of a mosaic BRCA2 carrier with a history of breast cancer, risk-reducing mastectomy and bilateral salpingo-oophorectomy was offered and taken up following discussion of the genetic result." (PMID 36068545, 2022). "Mutations in the BRCA1 gene are associated with triple-negative cancer and in the BRCA2 gene for estrogen receptor-expressed breast cancer." (PMID 35626173, 2022). "A RAD52 S346X truncation variant with reduced SSA activity decreases the risk of developing breast cancer in women with BRCA2 germline mutations." (PMID 36107942, 2022). "PARP inhibition has been shown to be a promising therapeutic strategy in homologous recombination repair-deficient tumors, such as BRCA1 and BRCA2-mutated breast cancer." (PMID 36139701, 2022). "Another important group of genes whose alterations are associated with genomic instability are called caretaker genes, for example, BRCA1 and BRCA2, whose mutations in family groups predispose to the development of breast cancer." (PMID 35954497, 2022). "Individuals with BRCA1/BRCA2 mutations have up to a 70% life‐time risk of developing breast cancer and up to 45% risk of developing ovarian cancer." (PMID 35128817, 2022). "Luminal subtype B accounts for 20–30% of invasive breast cancer cases and it is worth noting that most breast cancers genetically determined by BRCA2 gene mutation belong to this subtype." (PMID 35268340, 2022). "For example, BRCA1 and BRCA2, two major genes mapped to the long arms of chromosomes 17 and 13, determine predisposition to breast cancer." (PMID 34981672, 2022). "At this point, it is worth noting that mutations in two genes (BRCA1 and BRCA2) are the most significant causes of genetically determined breast cancer." (PMID 35268340, 2022). "The penetrance estimates for individuals with a pathogenic BRCA1 or BRCA2 variant range from 45 to 85% for breast cancer and from 10 to 65% for ovarian cancer, some of which can be explained by a polygenic background." (PMID 35983412, 2022). "Our study showed that it is mandatory to consider the complex interplay between the types of BRCA1 and BRCA2 pathogenic variants, age at primary breast cancer diagnosis, breast cancer subtype and stage, and received systemic treatment." (PMID 36580360, 2022). "The single nucleotide polymorphism (SNP) rs12652447 of FBXL7 is relevant to an increased risk of breast cancer in people carrying breast cancer gene 2 (BRCA2) mutations in breast cancer genome-wide association studies." (PMID 35906197, 2022). "Patients with hereditary mutations in BRCA1 or BRCA2 (gBRCA1/2) and breast cancer have distinct tumor biology, and encompass a predilection for brain metastasis (BM)." (PMID 35393462, 2022). "Pathogenic variants and germline mutations in BRCA1 and BRCA2 can increase the risk of developing breast cancer at a younger age, as these mutations represent more than 50% of all mutations in breast cancer-related genes in young women of specific populations." (PMID 36685821, 2022). "A recent case control association study and functional analysis of BRCA2 identified a hypomorphic missense variant (Y3035S) associated with a moderate risk of breast cancer." (PMID 35785170, 2022). "BRCA1/BRCA2 mutations and aberrant expression are common as the hallmarks of ovarian and breast cancer." (PMID 35328651, 2022). "Specially in women, BRCA1 or BRCA2 mutations result in a 57-65% or 45-55% risk of developing breast cancer by age 70 years, and a lifetime risk of 39-44% or 11-18% of developing ovarian cancer, respectively." (PMID 36463302, 2022). "On the contrary, the risk of developing basal or luminal A breast cancer was reduced to 81% or 77% for BRCA2 and BRCA1 pathogenic variants, respectively." (PMID 35451682, 2022).
breast cancer (continued). "For example, females carrying genetic mutations in the genes BRCA1 or BRCA2 have a greater chance of developing breast cancer." (PMID 35495618, 2022). "Approximately 62% of patients with breast cancer with a pathogenic variant (BRCA1 or BRCA2) undergo primary breast-conserving therapy." (PMID 36580360, 2022). "Since the discovery of the breast cancer susceptibility genes, BRCA1 and BRCA2, various other genes conferring an increased risk for breast cancer have been identified." (PMID 35039564, 2022). "Carriers of the BRCA1/BRCA2 mutation are estimated to have a 10-fold higher risk of developing breast cancer." (PMID 35626173, 2022). "The important factors which increase a man’s risk of breast cancer are; older age, “BRCA2/BRCA1” mutations, and increased estrogen levels, genetic history in family, and highly exposure to radiation." (PMID 35145999, 2022). "BRCA2 is associated with hereditary breast and ovarian cancer, and it is characterized by an increased risk for breast cancer, ovarian cancer, and to a lesser extent, other cancers (prostate cancer, pancreatic cancer, melanoma)." (PMID 36361862, 2022). "This implies that despite the low total heritability explained by polymorphisms in these genes, monitoring genetic variations in BRCA1 and BRCA2 is advantageous for the diagnosis of breast cancer in high-risk patients." (PMID 35743744, 2022). "In the BRCA2 gene, we identified 17 variants (1 variant in both ovarian and breast cancer patients, 6 distinct variants in BC patients, and 10 distinct variants in ovarian cancer patients)." (PMID 35409996, 2022). "Pathogenic variants in non-BRCA1/BRCA2 breast cancer susceptibility genes accounted for 1.8% of our cohort." (PMID 35039564, 2022). "Breast cancers with germline BRCA1 or BRCA2 pathogenic or likely pathogenic variants and biallelic inactivation show evidence of deficiency in homologous recombination repair." (PMID 36085046, 2022). "In our population cohort, BRCA1, and BRCA2 pathogenic and likely pathogenic variants have high risk of breast cancer." (PMID 35938029, 2022). "This is particularly relevant to BRCA 1/2 mutation carriers who confer a higher risk of breast cancer themselves, and are offered tamoxifen as chemoprophylaxis or treatment for breast cancer, particularly in BRCA2 carriers." (PMID 35323372, 2022). "There was a negligible increase in survival for carriers of the pathogenic variants BRCA1 and BRCA2 with TN breast cancer and who received any secondary prevention strategy compared with surveillance." (PMID 36580360, 2022). "BRCA1 and BRCA2 are associated with the DNA repair pathway and together, are the most common genetic cause for breast cancer, accounting for approximately 5% of all cases." (PMID 35813042, 2022). "Patients with breast cancer with BRCA1 or BRCA2 who underwent BCT have a significantly higher risk of a second primary ipsilateral breast event that is almost exclusively a new primary breast cancer rather than a true recurrence." (PMID 36580360, 2022). "The relationship between OC administration and the risk of breast cancer in BRCA2 mutation carriers was assessed in four trials." (PMID 36230696, 2022). "For example, mutations in BRCA1 and BRCA2 increase the risk of breast cancer, and mutations in RAD51 increase the risk of rectal cancer." (PMID 35991565, 2022). "In our analyses of any 2+ primary cancers and our breast cancer-specific analysis, we replicated associations for known pleiotropic genes, BRCA2 (pLOF, p = 3.76 × 10−11 and 1.91 × 10−9) and CHEK2 (pLOF + missense, p = 2.95 × 10−11 and 1.67 × 10−8)." (PMID 36199081, 2022). "Individuals carrying breast cancer susceptibility gene BRCA2 germline mutation are susceptible to breast cancer and other types of cancer." (PMID 35359344, 2022).